SLC2A7 (solute carrier family 2 member 7)
Description:
Probable sugar transporter. Even if its physiological substrate is subject to discussion, it is able to transport glucose and fructose. Does not transport galactose, 2-deoxy-d-glucose and xylose.
Synonyms: GLUT-7; hGLUT7; GLUT7
Tractability: Antibody: UniProt places it where antibodies can reach, with high confidence; its Gene Ontology location is reachable by antibodies, with high confidence; UniProt predicts a signal peptide or a membrane-spanning region.
Gene: Protein-coding gene on chromosome 1 (9,002,973 to 9,026,423, reverse strand). Ensembl gene ENSG00000197241.
Subcellular location: Cell membrane; Apical cell membrane
Pathways (Reactome):
Transport of small molecules: Cellular hexose transport
Gene Ontology:
Molecular function: D-glucose transmembrane transporter activity; fructose transmembrane transporter activity; protein binding; sugar transmembrane transporter activity; transmembrane transporter activity
Biological process: D-glucose transmembrane transport; fructose transmembrane transport; dehydroascorbic acid transport; hexose transmembrane transport; transmembrane transport
Cellular component: apical plasma membrane; plasma membrane; membrane
Genetic constraint (gnomAD): Loss-of-function variants: 51 observed, 48.56 expected, observed/expected ratio (o/e) 1.05, 90% interval 0.84 to 1.33. The upper end of that interval is the gene's LOEUF score, 1.33, which puts it in group 5 of 6, group 1 being the genes least tolerant of losing a copy. Missense variants: 683 observed, 674.1 expected, observed/expected ratio (o/e) 1.01, 90% interval 0.95 to 1.08. Synonymous variants: 308 observed, 295.04 expected, observed/expected ratio (o/e) 1.04, 90% interval 0.95 to 1.15.
Homologues: Orthologues: chimpanzee SLC2A7 (99% identical), macaque SLC2A7 (93% identical), pig SLC2A7 (82% identical), rabbit SLC2A7 (80% identical), rat Slc2a7 (77% identical), mouse Slc2a7 (76% identical), guinea pig SLC2A7 (72% identical), zebrafish slc2a15a (41% identical), tropical clawed frog slc2a9l (40% identical), zebrafish slc2a11b (39% identical), zebrafish slc2a15b (39% identical), tropical clawed frog slc2a7 (37% identical), and 46 more. Paralogues in human: SLC2A5 (58% identical), SLC2A9 (41% identical), SLC2A11 (38% identical), SLC2A4 (38% identical), SLC2A3 (38% identical), SLC2A1 (37% identical), SLC2A14 (37% identical), SLC2A2 (35% identical), SLC2A13 (26% identical), SLC2A10 (25% identical), SLC2A12 (23% identical), SLC2A8 (23% identical), and 1 more.
Diseases named in the same sentence as SLC2A7 in open-access papers:
SLC2A7 is named in the same sentence as 3 diseases in open-access papers, as found by Europe PMC text mining. Sharing a sentence is not in itself a finding about the gene and the disease. The quoted sentences say what the papers report.
gastric cancer (1 paper, 2025). A primary or metastatic malignant neoplasm involving the stomach. "Similarly, SLC2A7 has been identified as both a prognostic marker and a novel immunotherapy target for gastric cancer." (PMID 40824962, 2025).
tumor (4 papers, 2021 to 2024). "The Slc2a family, consisting of the genes Slc2a3, Slc2a4, Slc2a5, Slc2a6 and Slc2a7, is responsible for glucose transporters, and exhibited increased transcription in WT type mice tumor compared to KO tumor." (PMID 34685767, 2021). "According to data from the UALCAN database, LUAD patients’ tumor tissues had hypomethylation of SLC2A1, SLC2A2, SLC2A5, SLC2A6, SLC2A7, SLC2A11 and hypermethylation of SLC2A3, SLC2A10, and SLC2A14 compared to normal tissues." (PMID 36518662, 2022).
SLC2A7 also shares sentences with these, for which no sentence is quoted: Hepatic steatosis (1 paper).